STAT1 (signal transducer and activator of transcription 1)
Diseases named in the same sentence as STAT1 in open-access papers (continued):
Sharing a sentence is not in itself a finding about the gene and the disease.
inflammatory skin disease (9 papers, 2016 to 2024). Inflammatory skin disorders covers a broad category that includes many conditions ranging in severity, from mild itching to grave medical health complications These disorders are common in people of all ages and races. "Previous studies have reported the inhibitory effect of natural products and extracts from marine algae against inflammatory skin disorders by targeting the signaling pathway, leading to NF-κB and STAT1 activation." (PMID 32349358, 2020). "Similar to our study, several studies have reported the inhibitory effects of natural products against inflammatory skin diseases by targeting the signaling pathway leading to STAT1 and NF-κB activation." (PMID 30642008, 2019). "Inhibiting the activation of STAT1 is regarded as an important step to treat skin inflammatory diseases." (PMID 31007602, 2019). "Since STATs constitute a family of nuclear proteins that mediate the activation of various inflammatory cytokines, such as interleukins and interferons, inhibition of STAT1 phosphorylation is considered pivotal for the treatment of skin inflammatory disorders." (PMID 31007602, 2019). "Inhibition of STAT1 phosphorylation is considered to be an important step in treating skin inflammatory diseases." (PMID 27847527, 2016). "Besides, STAT1 and phosphor-STAT1 are primarily observed in the epidermis of inflammatory skin diseases, including lichen planus, psoriasis vulgaris, cutaneous lupus erythematosus and Hidradenitis suppurativa." (PMID 36091020, 2022). "Likewise, under AZ(−) conditions, THDC increased expression of genes belonging to the STAT1-57 module (P < 0.01), which is a set of genes activated by interferon signaling with elevated expression in inflammatory skin disease (e.g., MX2, IFIT3, IFI44)." (PMID 34445461, 2021). "Therefore, suppression of STAT1 phosphorylation could ameliorate AD-like skin inflammatory diseases." (PMID 33652742, 2021). "Our finding indicates that MHT inhibits production and expression of inflammatory chemokines in the stimulated keratinocytes by downregulating STAT1 phosphorylation, suggesting that MHT may be a possible therapeutic agent for inflammatory skin diseases." (PMID 27847527, 2016).
ischemic stroke (9 papers, 2019 to 2025). A stroke disorder caused by obstruction of blood flow to the brain, due to thrombotic (local blood clot formation) or embolic (due to a blood clot or other material traveling from another site) event. "In summary, these data suggest that STAT1 mKO potently shifts the phenotype of Mi/MΦ toward an inflammation-resolving phenotype after ischemic stroke." (PMID 37516843, 2023). "STAT1 is, therefore, a promising therapeutic target to harness beneficial Mi/MΦ responses and improve long-term outcomes after ischemic stroke." (PMID 37516843, 2023). "Expression of STAT1 was examined in the brain by flow cytometry and RNA sequencing after ischemic stroke induced by transient middle cerebral artery occlusion (MCAO)." (PMID 37516843, 2023). "While the pro-apoptotic role of STAT1 had been examined in the context of ischemic stroke in previous studies, its proinflammatory function had so far only been implicated in an indirect and correlative way in existing studies." (PMID 37516843, 2023). "STAT1 plays a significant role in promoting proinflammatory responses of Mi/MΦ following ischemic stroke." (PMID 37516843, 2023). "In summary, these data suggest that STAT1-deficient Mi/MΦ have less propensity for DAMP inflammatory activity in the ischemic brain than their counterpart in WT mice at the subacute stage after ischemic stroke, which may lead to reduced secondary neuronal death." (PMID 37516843, 2023). "On this backdrop, the present study aimed to directly investigate the specific role of STAT1 in the modulation of Mi/MΦ phenotype, inflammation, and long-term functional recovery after ischemic stroke, using a Mi/MΦ-targeted STAT1 knockout mouse model." (PMID 37516843, 2023). "In this study, we utilized a conditional knockout mouse model to delineate the role of STAT1 in modulating the function of Mi/MΦ following an ischemic stroke." (PMID 37516843, 2023). "Previous studies have found that constitutive STAT1 knockout reduces brain infarct volume 24 h after ischemic stroke, mainly through protection of neurons against acute apoptosis." (PMID 37516843, 2023). "At-RA showed potent therapeutic efficacy in ischemic stroke by attenuating neural inflammation through STAT1 signaling." (PMID 32040942, 2020). "Therefore, therapeutic electrical stimulations modulated the decrease in inflammatory cytokines, including IL-1β and TNF-α, in the ischemic stroke mice model by activating the STAT1 and NF-kB signaling pathways." (PMID 39062789, 2024). "We, therefore, examined whether selective deletion of STAT1 only in Mi/MΦ had an impact on acute brain injury after ischemic stroke." (PMID 37516843, 2023). "A total of 81 DEGs were in the molecular network of STAT1 targets, including genes encoding the proinflammatory cytokines IL-1β, tumor necrosis factor alpha (TNF-α), and IL-12, all of which were upregulated in microglia after ischemic stroke." (PMID 37516843, 2023). "The collective findings from our flow cytometry and RNA-seq analyses provide strong evidence that STAT1 is activated in brain Mi/MΦ after ischemic stroke, and may dictate the proinflammatory responses of Mi/MΦ at the subacute injury stage." (PMID 37516843, 2023). "Secondly, p38MAPK/STAT1 pathway may be a latent target for the prevention of ischemic stroke." (PMID 36572761, 2023). "In the context of ischemic stroke, elevated levels of IFN-γ contribute to neuroinflammation by activating STAT1 and NF-κB signalling cascades." (PMID 41388741, 2025). "It's known that both STAT1 and STAT3 are highly expressed in the brain, and reported to involve in the ischemic stroke and cognitive regulation 16-19, 43-44." (PMID 33859760, 2021). "The numbers of HMGB1+ neurons were similar in STAT1 mKO mice and WT mice 24 h after MCAO, suggesting similar neuronal injury and the initial trigger of proinflammatory responses at the acute stage after ischemic stroke." (PMID 37516843, 2023).
ischemic stroke (continued). "In contrast, a larger portion of astrocytes, oligodendrocytes and other CNS cells expressed STAT1 under baseline conditions compared to Mi/MΦ, but these cell types did not exhibit substantial alterations in response to ischemic stroke." (PMID 37516843, 2023). "It has been reported that ischemic stroke can induce the activation of STAT1 in the brain, yet the cell type(s) accountable for the increased activity of STAT1 have not been investigated thus far." (PMID 37516843, 2023). "It is not surprising that atRA inhibited STAT1 signaling in neutrophil after ischemic stroke." (PMID 31472680, 2019).
mastitis (9 papers, 2017 to 2024). Inflammation of breast tissue during lactation or postpartum due to an obstructed duct or infection. "Some of the DEPs such as TLR2, STAT1 and Cathelicidins were associated with inflammation of dairy mastitis." (PMID 36003411, 2022). "Downstream STAT1 is then phosphorylated and dimerizes into the nucleus, which induces the expression of M1-related marker genes, thereby promoting acute mastitis." (PMID 35769456, 2022). "EV-miR-221 secreted by mammary epithelial cells in mastitis and cardiac-derived EV-miR-155-5p in myocardial ischemia-reperfusion injury can induce STAT1 activation and induce M1-like macrophage polarization to aggravate the disease." (PMID 35769456, 2022). "It is highly recommended that further polymorphisms in STAT1 and SOCS3 and their associations with milk production and mastitis resistance traits be found out." (PMID 33202860, 2020). "The blue module was highly enriched in inflammatory responses and STAT1 was suggested to play an important role in mastitis development by regulating the immune related genes in this module." (PMID 32754201, 2020). "Many aspects of this pathway have been demonstrated in mice such as the regulation of lactation by prolactin via STAT5 and the SOCS proteins, the induction of STAT1 in conditions of sterile mastitis and the ability of STAT1 to regulate prolactin signaling." (PMID 29117179, 2017). "The EV-miR-221/SOCS1/STAT1/STAT3 axis not only increases the proportion of M1-like macrophages in the early stage of mastitis but also provides a new direction for exploring the pathogenesis of mastitis." (PMID 35769456, 2022). "In this regard, STAT1 has been shown to be important in immune cells in mastitis." (PMID 32754201, 2020). "STAT1 shows different regulatory activities, but is important for the response to growth hormone during mammary gland growth and development, as well as for the response to bacteria during mastitis: this latter function is particularly relevant to Lf as the protein has antibacterial properties." (PMID 38549172, 2024). "In addition, in this study, predicted activation status of transcription regulators showed the activation of STAT1, MITF, and various interferon regulatory factors in mastitis milk." (PMID 30271395, 2018).
pneumonia (9 papers, 2013 to 2026). An acute, acute and chronic, or chronic inflammation focally or diffusely affecting the lung parenchyma, caused by an infection in one or both of the lungs (by bacteria, viruses, fungi, or mycoplasma.). "Thus, a possible therapeutic approach for non-resolving pneumonia is boosting MDSC numbers via STAT1 inhibition in combination with antibiotics where suppression of unremitting inflammation along with complete elimination of the infectious agent is the desired goal." (PMID 24066282, 2013).
vitiligo (9 papers, 2021 to 2025). Generalized well circumscribed patches of leukoderma that are generally distributed over symmetric body locations and is due to autoimmune destruction of melanocytes. "Functional validation in a vitiligo mouse model and in vitro assays confirmed that pharmacological inhibition of STAT1 alleviates disease progression by suppressing macrophage‐driven inflammation." (PMID 41498037, 2025). "To investigate the functional role of STAT1 in macrophage‐mediated vitiligo pathology, we conducted in vitro experiments using RAW264.7 murine macrophages." (PMID 41498037, 2025). "The observed therapeutic effects provide compelling preclinical evidence supporting STAT1 as a promising target for vitiligo treatment." (PMID 41498037, 2025). "Despite these limitations, our results provide a proof‐of‐concept that STAT1 represents a pivotal regulator of inflammatory macrophage activation in vitiligo." (PMID 41498037, 2025). "Pharmacological inhibition of STAT1 by fludarabine effectively attenuates both processes, underscoring its therapeutic potential in vitiligo." (PMID 41498037, 2025). "In vivo, STAT1 inhibition by fludarabine ameliorated vitiligo progression by suppressing T cell activation and macrophage M1‐polarization." (PMID 41498037, 2025). "The identification of STAT1 as a key regulatory molecule provides a novel therapeutic target for vitiligo." (PMID 41498037, 2025). "Monobenzone was employed to induce vitiligo mice (VIT) while fludarabine was used as STAT1 inhibitor and served as the treatment group (VIT + Flu)." (PMID 41498037, 2025). "Previous studies have shown that STAT1, a transcriptional activator in vitiligo melanocytes, migrates into the nucleus to activate genes involved in cell proliferation and viability that can be activated by the IFN pathway." (PMID 36890149, 2023). "STAT1 has been implicated in macrophage activation and autoimmunity, but its role in vitiligo had not been experimentally validated." (PMID 41498037, 2025). "However, FHB therapy significantly hampered the increase of mRNA expression of Jak1, Jak2, Stat1, Stat2, and Stat3 in vitiligo mice, and this inhibitory effect was dose-dependent." (PMID 37575231, 2023). "Both JAK1 and JAK3 are upregulated in perilesional and lesional vitiligo skin compared to the levels observed in controls and the effects of INFγ on melanocytes, such as their senescence, may be attenuated through STAT1 inhibition." (PMID 34768860, 2021). "This analysis identified four genes—STAT1, VAMP5, LAP3, and TYMP—that exhibited both strong module membership and significant upregulation in vitiligo." (PMID 41498037, 2025). "To further investigate the effect of FHB on the JAK-STAT pathway in vitiligo mice at the transcriptional level, we used qRT-PCR to examine the influence of FHB on the mRNA expression of Jak1, Jak2, Stat1, Stat2, and Stat3 in the lesion region." (PMID 37575231, 2023). "Indeed, in total, our data demonstrated that IFN-γ in the vitiligo lesions stimulates fibroblast’s expression of CCL2 and CCL8 through activating the JAK2/STAT1 signaling pathway." (PMID 36672151, 2023). "Nevertheless, STAT1 is not the only transducer involved in vitiligo, but STAT3 is also increased in vitiligo lesions." (PMID 34768860, 2021).
acute kidney injury (8 papers, 2021 to 2026). Sudden and sustained deterioration of the kidney function characterized by decreased glomerular filtration rate, increased serum creatinine or oliguria. "Furthermore, this study is the first to identify CDK1 and STAT1 as independent risk factors for acute kidney injury in gastrointestinal cancer patients, positioning them as potential diagnostic biomarkers." (PMID 39911265, 2025).
acute lymphoblastic leukemia (8 papers, 2015 to 2022). Leukemia with an acute onset, characterized by the presence of lymphoblasts in the bone marrow and the peripheral blood. "TYK2 point mutations found in T-ALL (T-cell acute lymphoblastic leukemia) cell lines exhibited transformation potential via the STAT1/BCL2 pathway." (PMID 35042970, 2022). "Mimetic mediated agonism of miR-146a is shown to promote acute lymphoblastic leukemia Jurkat cells death by upregulating STAT1, an apoptosis promoting factor, and suppressing anti-apoptotic Bcl-1028." (PMID 31477775, 2019). "As an exception, STAT1 was shown to be an oncogenic driver in T-cell acute lymphoblastic leukemia (T-ALL) and ALK+ anaplastic large cell lymphoma (ALCL), and STAT1 is associated with the JAK2 exon 12 mutation in the progression of myeloproliferative neoplasms (MPNs)." (PMID 31817042, 2019).
allergic asthma (8 papers, 2009 to 2023). A asthma with a basis in a pathological type I hypersensitivity reaction. "Together, these data provide insight into the role of STAT1 and Th1 inflammation in chronic allergen exposure and has implications for understanding corticosteroid insensitivity in allergic asthma." (PMID 34755542, 2021). "Results of the triggering analysis performed over allergic asthma revealed that STAT1, MAPK13, and TLR4 are the top genes that play a trigger role according to the individual score." (PMID 33936056, 2021). "Based on the function of the gene products, the investigators divided the SNPs into four subgroups: innate immunity (IFNA13, IL15, STAT1, and TLR8), chemotaxis (CCL8, ITGB2, and VCAM), adaptive immunity (CD28 and STAT1), and allergic asthma (MS3A2, ADAM33, IL4R, and IL9R)." (PMID 19154602, 2009). "When looking at the cumulative score, the same combination of proteins (AKT1, STAT1, MAPK13, and TLR4) triggered 89.27% of the non-allergic asthma effector proteins and inclusion of the rest of proteins of interest would not substantially increase this percentage." (PMID 33936056, 2021). "Recent studies have shown that IL‐38 could inhibit the activation of intracellular STAT1/3, ERK1/2, P38 MAPK, and NF‐κB signaling pathways, and upregulate the expression of antiallergic response gene RGS13 and host defense‐related gene POU2AF1 in mice with allergic asthma." (PMID 37382260, 2023).
autoimmune thyroid disease (8 papers, 2018 to 2025). Inflammatory disease of the thyroid gland due to autoimmune responses leading to lymphocytic infiltration of the gland. "These patients display persistent autoinflammation and autoimmune phenomena, such as SLE, autoimmune cytopenias, autoimmune thyroid disease, T1D, and much like the STAT1 GOF patients." (PMID 37358695, 2023). "In conclusion, CMC alone, CMC with LRI infection, and CMC with autoimmune thyroid disease are clinical hallmarks of patients with STAT1-GOF." (PMID 33777053, 2021). "In light of the characteristic symptoms, treating physicians should consider the differential diagnosis STAT1 GOF in patients with CMC alone, CMC with lower respiratory tract infections, or CMC with autoimmune thyroid disease." (PMID 37140667, 2023).
co-infection (8 papers, 2014 to 2025). "RSV infection of MDDC caused MyD88-independent STAT1 phosphorylation, whereas BPZE1 activated MyD88-dependent signaling pathways; co-infection caused both pathways to be activated." (PMID 24967823, 2014). "Therefore, we analyzed the differential expression of STAT family genes and found that HIV-mono infection leads to the upregulation of STAT3 and STAT4, whereas co-infection results in the upregulation of STAT1 and STAT2." (PMID 41394852, 2025). "Considering the important role of macrophages in T. cruzi infection response and the paucity of studies involving co-infection with different strains, the present study evaluated the activation of STAT-1, -3, and -6 in polarized macrophages derived from THP-1 cells." (PMID 36389843, 2022). "Only some co-infection conditions resulted in fully activated STAT-1 and phosphorylated STAT-3." (PMID 36389843, 2022). "Altogether, these data demonstrate that Siglec-1 expression in human macrophages is controlled by IFN-I in a TB-associated microenvironment, and suggest the involvement of the IFN-I/STAT1/Siglec-1 axis in the pathogenesis of TB and co-infection with retroviruses." (PMID 32223897, 2020). "An even more significant increase in the phosphorylation level of STAT1 and STAT3 was detected in the co-infection group compared to any other group." (PMID 33968006, 2021). "The phosphorylation level of STAT1 and STAT3 was significantly increased after H9N2 and E. coli co-infection." (PMID 33968006, 2021). "After co-infection with NDV, the exogenous STAT1 expressed by plasmids were obviously degraded by NDV." (PMID 26859759, 2016).
cutaneous melanoma (8 papers, 2018 to 2024). A primary melanoma arising from atypical melanocytes in the skin. "Validation of STAT1 as a central hub gene in the protein-protein interaction network, coupled with functional experiments, underscores its potential as a therapeutic target in cutaneous melanoma." (PMID 38770150, 2024). "Consequently, we chose to validate the function of STAT1 in cutaneous melanoma through cellular experiments." (PMID 38770150, 2024). "Additionally, insights into the tumor microenvironment and validation of key genes like STAT1 open avenues for development of targeted therapies, immunotherapies, and potential biomarkers to guide clinical decision-making in cutaneous melanoma management." (PMID 38770150, 2024). "Moreover, our analysis of the TCGA skin cutaneous melanoma (SKCM) database revealed significantly higher methylation of promoters of genes presenting highly-correlated expression with STAT1 (a gene group that is enriched for cell autonomous immunity genes), as compared to randomly selected genes." (PMID 33668131, 2021). "Our correlation analysis of the transcriptomic data of 368 cutaneous melanoma samples revealed a positive correlation of PD-L1 to IFN-γ, STAT-1, IFN-γ driven CXCL10 and CXCL9 as well as to acidosis driven MMP9." (PMID 38102680, 2023). "The transcript expression of STAT1, STAT3, and IRF1, three key transcription factors of the IFNγ signaling cascade, were also lower in the TCGA UVM dataset compared to the TCGA cutaneous melanomas." (PMID 29977240, 2018). "Similarly, online TCGA/GTEx database analysis revealed that TET2/3 expression was significantly lower in skin cutaneous melanoma (SKCM) patients than in normal people and that TET expression positively correlated with that of STAT1/3." (PMID 36854755, 2023).